CRP (C-reactive protein)
Diseases named in the same sentence as CRP in open-access papers (continued):
Sharing a sentence is not in itself a finding about the gene and the disease.
depression (continued). "In a rat model of treatment-resistant depression, elevated CRP at baseline differentiated responders from non-responders to ketamine, an N-methyl-D-aspartate receptor antagonist with anti-inflammatory and antidepressant effects." (PMID 29764522, 2019). "ESR (3.5 mm/h, 95% CI 0.6 to 6.4 mm/h) was significantly higher in groups with depression, but not CRP (1.3 mg/dl, 95% CI − 0.9 to 3.4)." (PMID 29996916, 2018). "In conclusion, our meta-analysis found that elderly with depression had elevated peripheral levels of IL-1β, IL-6 but not CRP and TNF-α, and elderly with Alzheimer’s disease only had increased peripheral levels of blood IL-1β." (PMID 30104698, 2018). "Hitherto, no meta-analysis has specifically compared the peripheral levels of proinflammatory markers including IL-1β, IL-6, TNF-α and CRP between elderly with depression or Alzheimer’s disease and controls without any psychiatric disorder." (PMID 30104698, 2018). "In the subsample of HIV+ participants for whom CRP values were available, levels of CRP did not predict depression." (PMID 30249545, 2018). "In the general population, clinical evidence suggests an increased tendency for pro-inflammatory markers in persons with depression (increased interleukin [IL]-6, TNF-α, and CRP) relative to controls, a trend that normalizes following response to antidepressants." (PMID 30093853, 2018). "There were no systematic hs-CRP or IL-6 correlations with clinical PANSS subscale scores or Calgary depression self-ratings (data not shown)." (PMID 30322824, 2018). "Levels of IL-6, CRP and other markers of systemic inflammation appear to be higher in MS patients reporting symptoms of depression compared with patients who do not report such symptoms." (PMID 29294244, 2018). "Elderly with depression were nominal higher in their peripheral CRP levels than control participants but not statistically significant (pooled SMD: 0.499, 95% CI: 0.001–0.999, z = 1.961, p = 0.050)." (PMID 30104698, 2018). "Meta-analyses have gathered large evidence, particularly with C-reactive protein (CRP), interleukin-6 (IL-6), tumour necrosis factor-α (TNF- α) and IL-1 receptor antagonist (IL-1ra) being elevated among patients with depression." (PMID 30126458, 2018). "In a recent report from the Genome-Based Therapeutics Drugs for Depression (GENDEP) study, the association of CRP with depression severity was seen only in women but not men." (PMID 29329256, 2018). "And that the pro-inflammatory cytokines IL-1, IL-6, and tumor necrosis factor alpha (TNF-α), as well as C-reactive protein (CRP), may contribute to the initiation and progression of psychiatric diseases, such as depression." (PMID 30319458, 2018). "In PD, increased depressive symptoms as measured by the depression items of HADS and fatigue as measured by FACIT-f correlated with CRP (p = 0.006, β = 0.244 and p = 0.004, β = 0.243, respectively) and SAA (p < 0.001, β = 0.313 and p = 0.006, β = 0.235, respectively)." (PMID 30185816, 2018). "Study participants are then assigned into one of two study strata: either into the ‘Depression with inflammation’ stratum (CRP levels > 3 mg/L); or into the ‘Depression without inflammation’ stratum (CRP levels ≤ 3 mg/L)." (PMID 30126458, 2018). "Furthermore, in major depression and OSA, there are arguments for the presence of chronic systemic inflammation resulting in higher levels of C-reactive protein (CRP) and ferritin." (PMID 29202829, 2017). "Despite the special relationship between chronic inflammation and depression/OSA, plasma CRP and ferritin levels have never been studied as a risk factor for OSA in the general population or individuals with major depression." (PMID 29202829, 2017).
depression (continued). "Some previous studies detected increasing inflammatory markers such as CRP, interleukins, ferritin and erythrocyte sedimentation rate (ESR) in CKD patients, leading to deterioration of depression and subsequent malnutrition, atherosclerosis, cardiovascular morbidity and mortality in ESRD patients." (PMID 28487875, 2017). "When testing for interaction, the interaction term for gender × hs-CRP was significant for depression (β = 0.129, p = 0.008), not significant for apathy (β = 0.076, p = 0.12), and of borderline significance for optimism (β = -0.088, p = 0.074)." (PMID 28081723, 2017). "Notwithstanding its limitations, this study does provide evidence of cross-sectional and longitudinal relationships between depression and CRP in the underweight from a non-Western country, after adjusting for known confounders." (PMID 28128231, 2017). "However, a large Mendelian randomisation study found no causal association between increased CRP levels and depression in people with genetically elevated CRP, and also that inflammation may better stratify those who will or will not benefit from anti-inflammatory treatments." (PMID 28760142, 2017). "Similar to CRP, NLR was related to a later onset of depression." (PMID 29218020, 2017). "For example, there is evidence to suggest that pre-operative C-reactive protein levels predict depression experienced 6 months after CABG surgery and interferon-gamma measured in the days following surgery predicts depression 12-months after surgery." (PMID 27281345, 2016). "In addition, depressed and anxious individuals have higher levels of C reactive protein (CRP) levels, a marker for systemic inflammation, which is thought to play a role in the genesis of depression." (PMID 26771311, 2016). "Ordinal logistic regression predicts membership of the minimal, mild, moderate and severe fatigue groups using all 24 cytokines, WCC, lymphocytes, neutrophils, ESR, CRP, ESSDAI scores and dryness scores, as well as patient-reported depression, anxiety and pain." (PMID 27493792, 2016). "Future research should examine how psychological interventions for depression and/or PTSD might differentially affect emotion dysregulation and CRP concentrations and whether changes in one might then influence the status of the other." (PMID 27493807, 2016). "On the other hand, at least one study has found that somatic-vegetative symptoms of depression predicted 6-year change in IL-6 levels whereas baseline levels of neither IL-6 nor CRP were predictors of change in depressive symptoms in older individuals." (PMID 26631274, 2016). "They found that neither baseline IL-6 nor CRP levels behaved as predictors of the change in Beck Depression Inventory-II (BDI-II) scores during follow-up." (PMID 27918465, 2016). "Increased levels of inflammatory markers such as the cytokines CRP, IL-6 and TNF-α have been measured in patients with depression, regardless of a causal link between depression and inflammation." (PMID 26231223, 2015). "For example, in a study based on a multi-center trial involving depression patients, showed an interaction between antidepressants and C-reactive protein with patients with raised CRP more likely to respond to nortripytline than escitalopram." (PMID 25698954, 2015). "In conclusion, this cumulative meta-analysis confirmed higher mean levels of interleukin-6 and C-reactive protein in patients with major depression compared to non-depressed controls." (PMID 26065825, 2015). "CRP did not induce neophobia, anxiety or depression-like behavior in the NTg mice as tested in the corner test, dark and light box test and tail suspension test, respectively, nor increased the level of these behaviors in Tg mice (not shown)." (PMID 26335098, 2015). "Studies have shown that levels of interleukin (IL)-6 and C-reactive protein (CRP), and the immunologic complement component 4 (C4), but not C3, are significantly raised in patients with depression compared with controls." (PMID 23506529, 2013).
depression (continued). "Prior studies with a racially diverse sample found a link between history of major depression and C-reactive protein levels ≥.22 mg/dL, but this work did not examine hsCRP, as the assay used was not high sensitivity." (PMID 24151548, 2013). "Additional analyses revealed that a significant relationship was found between depression and elevated CRP levels only in patients not taking statins." (PMID 23227360, 2012). "After 2 months of treatment of these patients, Hamilton rating scale for depression (HRSD scale), C-reactive protein (CRP), erythrocyte sedimentation rate (ESR) and white blood cell (WBC) count were measured and compared to their respective baseline values before starting treatment." (PMID 21701640, 2011). "When comparing women confirming past but not present depression (n = 71) and women without a history of depression (n = 71), harm avoidance did not correlate with serum levels of CRP in either of the groups." (PMID 18384670, 2008). "The correlations between CRP, on the one hand, and harm avoidance and self-directedness, on the other, remained significant also after exclusion of women self-reporting ongoing depression (data not shown)." (PMID 18384670, 2008). "On the other hand, the available data do not exclude the possibility that CRP levels are slightly elevated also after recovery, and between episodes in recurrent depression." (PMID 18384670, 2008). "Additionally, elevated serum levels of proinflammatory cytokines (e.g., CRP, IL-6, TNF-α) in depression cross the blood-brain barrier to directly inhibit sleep-regulatory functions in the prefrontal cortex and hypothalamus, leading to sleep fragmentation and reduced slow-wave sleep 67-69." (PMID 41399386, 2026). "Most importantly, although anti-inflammatory interventions—for instance, infliximab—have shown promise in inflammatory subtypes of depression (e.g., patients with elevated CRP), prospective interventional trials targeting populations with depression–cancer comorbidity are conspicuously absent." (PMID 41000397, 2025). "Increased concentrations of biomarkers of low-grade inflammation such as C-reactive protein (CRP; >3 mg/L) have been identified, together with elevated levels of interleukin (IL)-6 and other inflammatory cytokines in blood and cerebrospinal fluid of patients with depression." (PMID 38545720, 2025). "In RA, elevated CRP levels have been consistently associated with greater depressive symptom severity, while in MS, increased peripheral inflammation, particularly heightened levels of IL-6 and CRP, appears to differentiate individuals with comorbid depression from those without." (PMID 40943152, 2025). "Similarly as in IBD patients, acute-phase proteins such as CRP are increased in patients affected by depression, while negative acute-phase proteins such as albumin are decreased." (PMID 40807142, 2025). "However, neither anxiety score, depression score, nor the interaction term anxiety∗depression contributed to variance in CRP level." (PMID 40823322, 2025). "Physical comorbidities could mask depression contributions to inflammation and depressed patients prone to immune activation may not be reliably identified based on CRP." (PMID 39959848, 2025). "Chronic inflammation, with raised levels of pro-inflammatory cytokines such as IL-6 and TNF-α, and C-reactive protein (CRP), affect the central nervous system—specifically, dopaminergic function in the basal ganglia, which may result in depression, fatigue, and cognitive and motor slowing." (PMID 40487528, 2025). "In particular, individuals with poor emotional regulation or low sleep quality were more vulnerable to the negative effects of elevated inflammatory markers, such as CRP, IL-6, and TNF-α, associated with greater fatigue, somatic complaints, depression, and anxiety." (PMID 41333345, 2025).
depression (continued). "Moreover, patients with severe depression have elevated levels of NLR and other anti-inflammatory cytokines (such as interleukin [IL]-10 and C-reactive protein) compared to healthy individuals, and elevated NLR levels can increase the risk of suicide in depression patients." (PMID 40458804, 2025). "No significant PGS_CRP effects on depression or internalizing psychopathology." (PMID 40630521, 2025). "Future research could further elucidate how this pathway interacts with other systemic inflammation markers, such as the C-reactive protein to lymphocyte ratio (CLR), to deepen our understanding of the inflammatory underpinnings of depression and potentially guide new therapeutic interventions." (PMID 40901264, 2025). "Laboratory data such as inflammatory markers (e.g., CRP, IL-6), which could have further explained the relationship between malnutrition and depression, were not included in the analysis." (PMID 41295296, 2025). "Subjects with unipolar depression have a significant and positive relationship of CRP serum levels with the “concentration difficulties” item (Rho = 0.262), and IL-6 also with the items “concentration difficulties” (Rho = 0.278) and “lassitude” (Rho = 0.345) on the MADRS Depression Rating Scale." (PMID 38785543, 2024). "Measures included the Hamilton Depression Rating Scale (HDRS-17) and the Beck Scale for Suicide Ideation/Suicide Severity Index (BSS/SSI), alongside sociodemographic data, alcohol, tobacco use, and morning blood samples, measuring plasma ACTH, cortisol, DHEA, CRP, and IL-6." (PMID 38737407, 2024). "Interestingly the objective measurement of CRP did not play a significant role, which suggests pain as one of the leading factors for depression in RA patients." (PMID 39845811, 2024). "Finally, improving depression scores did not alter the biochemical parameters of gut inflammation, including serum IL-6, CRP, or fecal calprotectin levels." (PMID 38839073, 2024). "For instance, one study included only a female population and found that HSCRP is an independent prognostic marker for severe depression in women; another study did not fully utilize CRP as a continuous variable to deeply analyze its relationship with depression." (PMID 39902244, 2024). "We found that the samples in GWAS on broad depression, MDD, anxiety disorder, PTSD, AN, blood metabolites, CRP, sleep duration, insomnia, and BMI might be overlapped with the samples from GWAS on IBS, because they all contained the participants from UK Biobank." (PMID 38352653, 2024). "Our results do not support the recent suggestion that serum CRP may lower anxiety and depression symptoms." (PMID 37217205, 2023). "We show that apparent significant findings from univariable MR analyses of CRP do not persist in MVMR analyses adjusting for BMI, indicating that BMI may be the primary driver of the observed association between CRP and depression outcomes." (PMID 37710313, 2023). "Although our results support a mediating role of systemic low-grade inflammation in the association between excess body weight and somatic depressive symptoms, CRP is not capable of crossing the blood–brain barrier and cannot directly affect depression-related brain regions." (PMID 36462595, 2023). "Our findings do not support the recent suggestion that serum CRP may lower anxiety and depression symptoms." (PMID 37217205, 2023). "The CRP levels were not measured and used as an exclusion criteria for any inflammation or infection, as this protein has been found significantly upregulated in a subgroup of depression patients." (PMID 37575572, 2023). "Our particular attention was drawn to ankylosing spondylitis (AS), which is characterized by chronic inflammation and frequent occurrence of depressive disorders, but probably there is no direct link between C-reactive protein (CRP)-mediated inflammation and depressive symptoms." (PMID 37646896, 2023).
depression (continued). "Similarly, further studies should be implemented for investigating the different MDD phases and the different clinical depression subtypes, in order to identify whether a specific subgroup of MDD patients may benefit from monitoring CRP levels from a clinical and therapeutic point of view." (PMID 35163538, 2022). "There is therefore a complex relation between depression and CHD regardless of comorbidity with PTSS, but how this may be relevant to persistently increased CRP risk-categories after MI remains to be further investigated." (PMID 35566447, 2022). "Furthermore, MVMR analyses showed that adjusting the effect of smoking on depression for CRP levels did not result in a significant estimate for the effect of CRP levels." (PMID 36057695, 2022). "Depression is accompanied by the changes in the levels of inflammatory and trophic factors, including interleukins (IL-1beta, IL-2, IL-6), interferon alpha (IFN-alpha), tumor necrosis factor alpha (TNF-alpha), C-reactive protein (CRP), and brain derived neurotrophic factor (BDNF)." (PMID 35455388, 2022). "However, no significant linear relationship was found between CRP levels and headache frequency, the severity of anxiety, or depression." (PMID 36313504, 2022). "However, severity of depression or anxiety, age, education, income, race/ethnicity, SSRI/SNRI, and several other variables were not individually associated with CRP concentrations." (PMID 35821205, 2022). "We applied summary statistics from GWAS of depression, CAD, body mass index (BMI), systolic blood pressure (SBP), diastolic blood pressure (DBP), high-density lipoprotein (HDL), low-density lipoprotein (LDL), triglycerides (TG), total cholesterol (TC), (T2D), c-reactive protein (CRP)." (PMID 35560157, 2022). "Our results did not provide strong support for a potentially causal relationship between CRP and depression or vice versa, though several observational studies have demonstrated that patients with depression have significantly higher CRP levels when compared to those without depression." (PMID 36057695, 2022). "Inflammation is not the only physiological state in which cytokines such as CRP and IL-6 serve a function, which complicates any inferences we may make about their role in HIV-associated depression." (PMID 35618889, 2022). "In separate analyses, CRP was only predictive of new onset of depression in men, but not in women." (PMID 33500534, 2021). "Clinical studies have indicated that patients suffering from depression showed significantly higher levels of proinflammatory cytokines, including interleukin-1β (IL-1β), interleukin-6 (IL-6), tumor necrosis factor alpha (TNF-α), C-reactive protein (CRP), and inflammasome, than healthy people." (PMID 33466877, 2021). "The CRP levels were not related to symptom severity during depression and mania." (PMID 33672126, 2021). "Thus CRP-related increases in proton density—a plausible marker of extracellular oedema—and changes in functional connectivity were anatomically co-localised with DMN nodes that also demonstrated significantly reduced hubness in depression." (PMID 34535766, 2021). "However, when testing the difference in simple slopes across CRP cut-points with e-cigarette use, CRP level, and their interaction in the full model logistic regression included, inflammation does not moderate the relationship between vaping and depression." (PMID 34639705, 2021). "CRP elevation and GE did not explain the whole variance of depression in our sample." (PMID 34764926, 2021). "Increased levels of proinflammatory biomarkers (including CRP, IL-6, and TNF-α) were found in patients with depression, whereas NSAIDs treatment significantly inhibited the inflammatory response and reduced the suicidal ideation and depression symptoms in depressed patients." (PMID 32522211, 2020).